MYH4 (myosin heavy chain 4)
Description:
Muscle contraction.
Synonyms: MyHC-2b; MyHC-IIb; MYH2B
Tractability: PROTAC: ubiquitination databases record sites on it.
Gene: Protein-coding gene on chromosome 17 (10,443,290 to 10,469,559, reverse strand). Ensembl gene ENSG00000264424.
Subcellular location: Cytoplasm, myofibril
Subcellular location (Human Protein Atlas): Focal adhesion sites
Gene Ontology:
Molecular function: double-stranded RNA binding; actin filament binding; ATP hydrolysis activity; microfilament motor activity; ATP binding; cytoskeletal motor activity
Biological process: muscle contraction; actin filament-based movement; ATP metabolic process; muscle filament sliding
Cellular component: myofibril; cytoplasm; muscle myosin complex; myosin filament; myosin II complex; sarcomere; myosin complex
Genetic constraint (gnomAD): Loss-of-function variants: 199 observed, 239.1 expected, observed/expected ratio (o/e) 0.83, 90% interval 0.74 to 0.94. The upper end of that interval is the gene's LOEUF score, 0.94, which puts it in group 3 of 6, group 1 being the genes least tolerant of losing a copy. Missense variants: 2,128 observed, 2,393.2 expected, observed/expected ratio (o/e) 0.89, 90% interval 0.86 to 0.92. Synonymous variants: 754 observed, 859.37 expected, observed/expected ratio (o/e) 0.88, 90% interval 0.83 to 0.93.
Homologues: Orthologues: chimpanzee MYH4 (99% identical), macaque MYH4 (98% identical), rabbit MYH4 (96% identical), pig MYH4 (95% identical). Paralogues in human: MYH1 (94% identical), MYH2 (92% identical), MYH8 (90% identical), MYH3 (83% identical), MYH13 (81% identical), MYH7 (81% identical), MYH6 (80% identical), MYH7B (67% identical), MYH15 (60% identical), MYH11 (42% identical), MYH9 (41% identical), MYH10 (41% identical), and 32 more.
Diseases named in the same sentence as MYH4 in open-access papers:
MYH4 is named in the same sentence as 39 diseases in open-access papers, as found by Europe PMC text mining. Sharing a sentence is not in itself a finding about the gene and the disease. The quoted sentences say what the papers report.
breast carcinoma (2 papers, 2020 to 2025). "Altogether, our data highlight how MYH4 can suppress breast cancer and indicate how it guards against replication-associated vulnerabilities, offering significant potential for therapeutic exploitation in targeting these cancers." (PMID 40454487, 2025). "According to Kaplan–Meier plotter, low expression of FOSB, GPR153, and MYH4 is associated with poor RFS in breast cancer patients." (PMID 32679794, 2020). "Moreover, our in vivo findings indicate Myh4 as a chromosome 17p gene involved in mammary tumor progression." (PMID 40454487, 2025).
Sepsis (2 papers, 2017 to 2020). Sepsis is defined as life-threatening organ dysfunction caused by a dysregulated host response to infection. "Because IL-1β treatment leads to decreased Myh2, Myh4, and Myh7 expression in myocytes, reduced muscular MyHC expression during sepsis might be caused by IL-1β." (PMID 28097512, 2017). "Sepsis led to a decreased Myh4 expression (sham + vehicle vs. CLP + vehicle: −56%, P < 0.01; sham + BMS‐345541 vs. CLP + BMS‐345541: −15%, n.s.), which was attenuated by 34% by BMS‐345541 (P < 0.05)." (PMID 31441598, 2020). "Accordingly, sepsis‐induced reduction in Myh4 expression and induction of Trim63/MuRF1 and Fbxo32/Atrogin1 expression was reversed by BMS‐345541." (PMID 31441598, 2020).
breast tumors (1 paper, 2025). "Consistent with prior genetic analyses, our survey indicated the loss of MYH4 due to segmental loss on chromosome 17p in breast tumors and various other cases." (PMID 40454487, 2025).
Cachexia (1 paper, 2024). Severe weight loss, wasting of muscle, loss of appetite, and general debility related to a chronic disease. "In fact, the population of Myh2+ myonuclei representing type IIa was clearly diminished with cachexia, whereas Myh4+ myonuclei (type IIb) were enriched." (PMID 39001644, 2024).
cardiomyopathy (1 paper, 2022). A disease of the heart muscle or myocardium proper. "Driven by adeno‐associated virus (AAV), sgRNA was delivered to the Myh4 locus to induce an accurate and rapid depletion of cardio‐relevant genes and subsequently show severe cardiomyopathy." (PMID 35845351, 2022).
cervical cancer (1 paper, 2023). A primary or metastatic malignant neoplasm involving the cervix. "The results showed that high expression of MYH1, MYH4, FGG, and DEPP1 was associated with shorter overall survival of patients with cervical cancer; high expression of SULT1E1, RAB3C, CXCR3, and PROX2 was associated with longer overall survival of patients with cervical cancer." (PMID 37350944, 2023). "High expression of MYH1, MYH4, FGG, DEPP1, and ZBTB16 was associated with shorter overall survival of patients with cervical cancer; high expression of SULT1E1, RAB3C, CXCR3, and PROX2 was associated with longer overall survival of patients with cervical cancer." (PMID 37350944, 2023).
Fukuyama congenital muscular dystrophy (1 paper, 2011). "We examined transcripts encompassing the CDSs for M-RAS, encoding a muscle-specific RAS protein; the myosin heavy chain protein MYH4, which is primarily expressed in skeletal muscles; and fukutin (FKTN), the locus for Fukuyama congenital muscular dystrophy." (PMID 21232131, 2011).
leiomyosarcoma (1 paper, 2020). An uncommon, aggressive malignant smooth muscle neoplasm, usually occurring in post-menopausal women. "The downregulation of skeletal myosins (MYH1, MYH2, MYH4) by bortezomib is not easily explained, since skeletal myosins are typically markers of rhabdomyosarcoma rather than leiomyosarcoma." (PMID 32117764, 2020).
sarcoma (1 paper, 2025). A usually aggressive malignant neoplasm of the soft tissue or bone. "We exclusively observed sarcomas in the main tumors of the NT group, while in the Myh4 group we observed adenocarcinomas and sarcomas and in the Atm group, mixed carcinoma and sarcomas were observed." (PMID 40454487, 2025).
vitamin D deficiency (1 paper, 2016). A nutritional condition produced by a deficiency of VITAMIN D in the diet, insufficient production of vitamin D in the skin, inadequate absorption of vitamin D from the diet, or abnormal conversion of vitamin D to its bioactive metabolites. "Given that we did not independently quantify MYH4 and 9, it is possible that these proteins do play a role in vitamin D deficiency induced alterations in lung function." (PMID 27121020, 2016).
tumor (8 papers, 2012 to 2025). "The overall survival curve for the Atm group indicated a 5-fold increased risk of tumor events, whereas the Myh4 group indicated an 8-fold increased risk, relative to the NT group." (PMID 40454487, 2025). "This analysis suggests that the loss of Myh4 resulted in a subtle phenotypic change, leading to a spectrum of tumor types that may indicate a broader cellular origin of tumorigenesis compared with NT tumors." (PMID 40454487, 2025). "Interestingly, tumour‐induced alterations in the expression of Atrogin1, MuRF1, Pik3r1, Pdk4, Myh4, Myh2 and Myh1 were attenuated in EDA2R‐deficient muscles, implying that the EDA2R pathway contributes to the reprogramming of muscle gene expression during cancer cachexia." (PMID 39001644, 2024). "An enrichment analysis with Toppgene revealed that over 10 of the 17 significantly upregulated genes in the tumours of the female mice were skeletal muscle genes such as Acta1, Actn3, Myh2, Myh4 and Des." (PMID 37840045, 2023). "Down-regulated genes in the irradiated tumor in significantly enriched GO categories related to smooth muscle and pericytes such as Des, Myh4, Ttn and Mybpc2." (PMID 22927920, 2012). "We did not observe significant differences in tumor-free survival of Atm (P = 0.426) or Myh4 (P = 0.216) when compared to NT mice, with median tumor-free survival of 241 days for the Myh4 group, 244 days for the Atm group, and 319 days for the NT control group." (PMID 40454487, 2025). "This indicates that Myh4 might not be contributing to tumor onset per se, but rather aggravates the cancer progression." (PMID 40454487, 2025). "We compared the gene expression levels between normal and tumor tissues of COAD patients from TCGA and found that OXSM was significantly downregulated (p = 5.20 × 10–9), while TRIP6 (p = 5.00 × 10–12), MYH3 (p = 6.70 × 10–3), and MYH4 (p = 6.41 × 10–7) were upregulated in COAD tissues." (PMID 37524774, 2023). "CCL2 siRNA treatment of 4T1 tumor-bearing mice increased myofiber size as indicated by measurements of cross-sectional area and Feret diameter, increased MYL expression, and reduced expression of total MYH but not MYH4." (PMID 38973385, 2024).
cancer (5 papers, 2017 to 2025). A tumor composed of atypical neoplastic, often pleomorphic cells that invade other tissues. "Regarding the remaining DEPs, Myh4, Acta1, Tnnt3, Mb, Ttn, Actn2, Myh7, Myl1, Mybpc2, Myl3, and Tnnc2 are associated with several cancers." (PMID 39861068, 2024). "Collectively, our genetic and functional study of MYH4 provides valuable insights that highlight its role in cancer progression." (PMID 40454487, 2025). "Furthermore, the identification of additional genes, particularly those within the actin-myosin pathway, that exhibit synthetic lethal interactions with MYH4 holds promise for the discovery and therapeutic exploitation of novel cancer vulnerabilities." (PMID 40454487, 2025). "Interestingly, the motor protein cluster disappeared by month 6 with the exceptions of Acta and Myh4, indicating that these proteins are primarily required at the early stage of cancer development." (PMID 33801718, 2021).
MYH4 also shares sentences with these, for which no sentence is quoted: Obesity (3 papers); sarcopenia (2); adenocarcinoma (1); atherosclerosis (1); autism (1); cardiac disease (1); Carney complex (1); ciliopathy (1); connective tissue disorder (1); deafness (1); dystrophin deficiency (1); Herpes Simplex (1); Hydrocephalus (1); hypertrophic cardiomyopathy (1); hypothyroidism (1); keratitis (1); limb-girdle muscular dystrophy (1); muscle degeneration (1); muscle disorders (1); muscular disorders (1); muscular dystrophies (1); Retinitis pigmentosa 67 (1); retinoblastoma (1); rhabdomyosarcoma (1); spinal muscular atrophy (1); teratoma (1); Thrombocytopenia (1).